CXCR3 (C-X-C motif chemokine receptor 3)
Diseases named in the same sentence as CXCR3 in open-access papers (continued):
Sharing a sentence is not in itself a finding about the gene and the disease.
tumor (continued). "Among the chemokine receptors expressed by CIKs, CXCR3 and CD62L were elevated in CD8+ T cells, representing the trafficking ability to inflamed tumor sites." (PMID 36598909, 2023). "Therefore, we hypothesized that Cxcr3 may influence tumor-specific T cell fate." (PMID 36472588, 2023). "EMP3 knockout combined with anti-PD-1 therapy resulted in tumor growth inhibition by promoting T cell (CD4+ and CD8+) infiltration mediated by the CXCR3 axes." (PMID 38104126, 2023). "ILC1 also upregulates CXCR6, CCR5, CXCR3, and CCR1 which can recruit RORγt+ ILC3s to the tumor leading to the inhibition of tumor growth." (PMID 38567059, 2023). "CXCR3/CXCL9/CXCL10/CXCL11 axis leads to recruitment of tumor-promoting immune cells, including TAMs, T cells, etc., thus favoring tumor growth and metastasis." (PMID 37818357, 2023). "The results demonstrate that CXCR3 and LFA-1 in CD8+ T cells play significant roles in anti-tumor immunity." (PMID 36688994, 2023). "CXCR3 and CX3CR1 are mainly responsible for infiltrating tumour-inhibitory lymphocytes into the tumour microenvironment, further confirming the results of immune cell infiltration." (PMID 37880315, 2023). "NLRC3 showed moderate and strong correlations with CCL5, CXCL9, CXCL10, CXCL11, CXCR3, and CCR5, resulting in an increased recruitment of NK cells, TH1 cells, and CD8+ T cells in tumor tissues." (PMID 36808166, 2023). "However, the role of Cxcr3 on a tumor-specific T cell response in PDA is unknown." (PMID 36472588, 2023). "CXCR3 and CCR2 signaling pathways lead to the recruitment of tumor-promoting immune cells such as TAMs, T cells, and myeloid-derived suppressor cells (MDSC)." (PMID 37626511, 2023). "In PAAD, sensory-neuron-derived mediators CXCL10 and CCL21 pass through complementary receptors CXCR3 and CCR7 on tumor cells, activating AKT, MEK, and RAC signaling pathways in tumor cells to mediate migration." (PMID 36900158, 2023). "CXCR3 inhibition reduced CD8+ T-cell infiltration and accelerated tumor progression in mouse models." (PMID 38035101, 2023). "CXCL-9 is an IFN-γ inducible chemokine that attracts various CXCR-3-expressing effector immune cells including CD8+ and CD4+ T-cells and also NK cells, and thereby changes the tumor microenvironment to an anti-tumor phenotype." (PMID 37958417, 2023). "Both CXCR3 and CXCR6 were expressed at highest frequencies on tumor center trNK cells and CD8+ TRM cells, respectively." (PMID 37448786, 2023). "In their experiment on transgenic mice and tumour cell lines, they observed that TGB-β receptor-knockout mice exhibited higher CXCR3 and CD8+ T cell tumour infiltration than TGF-β receptor-positive cells." (PMID 36761981, 2023). "In contrast, CD8+ TRM cells expressing only CXCR3 (population 14) and co-expressing CXCR3, CCR2, and CCR5 (population 2) were largely confined to the distal non-tumor area." (PMID 37448786, 2023). "As a result, CXCL9 and ten from dendritic cells anchor CTLs to the vascular endothelium via CXCR3 in the bloodstream, effectively inducing CTL infiltration into the tumor." (PMID 37046727, 2023). "CXCL12 not only binds to CXCR4, but also to CXCR3 and DPP4 on tumor cells in our study, which is consistent with previous reports." (PMID 37719863, 2023). "This increased CXCL10 induction correlated with higher frequency of intratumoral CXCR3+ CD8+ T cells, demonstrating that reversal of epigenetic silencing of STING using a demethylating agent can promote tumor infiltration of CD8+ T cells." (PMID 36949064, 2023). "It is a chemokine that interacts with T cells by binding CXCR3, inducing the recruitment of CD8+ lymphocytes to the tumor microenvironment and inducing the differentiation of inflammatory T helper type 1 (Th1) and Th17 CD4 cells." (PMID 36900006, 2023).
tumor (continued). "Compartmental analysis of exhausted T cell subsets shows that primarily undifferentiated, stem-like, tumor-specific CD8+ T cells expand in the blood; these cells express the chemokine receptor CXCR3, which is required for migration into tumors." (PMID 37045833, 2023). "PPARα agonist induced chemokine expression in the tumor (CXCL9/10) together with the respective receptor (CXCR3) on CD8+ T-cells, allowing their recruitment into the tumor tissue microenvironment." (PMID 37686465, 2023). "As expected, there was a higher macrophage presence for HPVOPC tumors compared to benign tissue, and this also validated that CXCR3 and CXCL9 were highly expressed in tumor cells themselves, as well as macrophages." (PMID 37686653, 2023). "Subpopulation analyses of tumor-specific CD8+ T cells showed that not only total, but also stem-like CXCR3+ cells expanded." (PMID 37045833, 2023). "Although CD8+ T cells are minor populations in CXCR3+ PBMCs, ULCA treatment also increased the numbers of CD8+ T cells at the tumor site." (PMID 36989357, 2023). "Several chemokine ligands are expressed by the tumor: CCL17 and CCL22 promote recruitment of CCR4+ Tregs, while CXCR3—along with its ligands, CXCL9 and CXCL10—drives cytotoxic lymphocyte trafficking into the GBM tumor site." (PMID 37443804, 2023). "M1-like macrophages penetrate the TME during the early phase of tumor by antigen presentation and secreting CXCL9, CXCL10, and CXCL11, which chemoattract CXCR3-expressing effector immune cells like CD8+ cytotoxic T cells and NK cells." (PMID 38035101, 2023). "These chemokines have been identified as the dominant mediators for the recruitment of CXCR3+ and CCR5+ tumor-specific T lymphocytes into the tumors and their intratumoral expression correlated with favorable clinical outcomes in patients with melanoma." (PMID 36949064, 2023). "Mechanistically, T-αFGL2 cell treatment increased the number of CD69+CD8+ brain-resident memory T cells in tumor-bearing mice via a CXCL9/10 and CXCR3 chemokine axis." (PMID 36759517, 2023). "These DCs, along with macrophages and tumor cells, secrete chemokines like CXCL9 and CXCL10, which aid in recruiting circulating CXCR3-expressing CD8+ T cells to the tumor site to exert cytotoxic effects on tumor cells." (PMID 37920470, 2023). "Some tumor cell lines express CXCR3, a receptor for IFN-inducible chemokines, and it has been reported that chemokines produced by tumor cells stimulate cell motility and are involved in tumor progression and metastasis." (PMID 37218983, 2023). "Other chemokine receptors, such as CCR5 and CXCR3, are also expressed by tumor CD8+ TRM cells and are probably involved in the residency of these cells in the inflammatory tumor microenvironment." (PMID 37545498, 2023). "It was shown that ex vivo expansion of NK cells in the coculture of IL-2 and feeder cells (EBV-LCLs) significantly upregulated the expression of CXCR3 on NK cells, resulting in increased migratory capacity toward CXCL10-producing tumor cells in vitro." (PMID 38264648, 2023). "IHC staining showed stronger expression of CD3D, CD3E, CXCR3 and IL2RG in tumor tissue compared to normal tissue." (PMID 37509334, 2023). "Stem-like tumor-specific CD8+ T cells expanded mostly in the peripheral blood; these highly expanded cells expressed CXCR3." (PMID 37045833, 2023). "This reduction in CD8+ T cell recruitment upon CXCR3 blockade also mitigated the anti-tumor effects of combined EZH2 suppression and T/P-induced senescence and reversed PDAC tumor regressions." (PMID 37142692, 2023). "HPVOPC tumors showed higher expression when compared to benign oropharynx tissue for both CXCR3 and CXCL9, and they demonstrated higher expression in the tumor itself than in the surrounding stromal cells." (PMID 37686653, 2023).
tumor (continued). "The CTSB on tumor cells surface can remove the autoreactive lymphocytes and degrade these cytotoxic effector molecules (such as IgG and chemokines CXCR3, CXCL9, CXCL10) synthesized from tumor-suppressive infiltrating immune cells." (PMID 35277559, 2022). "Among the chemokines known to attract CD8+ T cells into the tumor are CXCL9, CXCL10, and CXCL11, all of which bind to the chemokine receptor CXCR3 expressed at the surface of CD8+ T cells." (PMID 35439168, 2022). "Typically, LAG-3 and PD-1 expressions were greater in the tumor, while CX3CR1, CXCR3, and CD27 expressions were lower compared to the PB levels." (PMID 35003893, 2022). "In bladder cancer, the tumor-associated dendritic cells were found to secrete CXCL9, increasing PD-L1 expression in the tumor cells via the CXCR3/STAT3/AKT signaling pathway, thus resulting in the inhibition of anti-tumor adaptive immunity." (PMID 36131933, 2022). "The chemokine CXC motif receptor 3 (CXCR3), the CXCL9, CXCL10 and CXCL11 specific receptor, participates in the tumor migration, invasion, angiogenesis and immunity and are mainly expressed on monocytes, effector T cells, NK lymphocytes and cancer cells." (PMID 36030223, 2022). "CXCL10 also potentiates the accumulation of CXCR3+ effector T cells, particularly CD8+ T cells, into the tumor microenvironment and directly suppresses tumor growth in various cancers." (PMID 36275816, 2022). "Meanwhile, CXCL10 has been shown to induce tumor progression and metastasis through CXC motif chemokine receptor 3 (CXCR3) in melanoma, colon cancer, and breast cancer." (PMID 36612121, 2022). "As the tumor size increases, the presence of CD4+ CCR6+ CCR5+ CXCR3− and CD4+ CCR6+ CCR5− CXCR3− T cells also increase, which means that Th17/Th1 and Th17 cells’ presence is directly correlated with the size of the tumor in CRC liver metastasis." (PMID 36551555, 2022). "Fibroblast-secreted CXCL 9/10 binds the C-X-C Motif Chemokine Receptor 3 (CXCR3) on the invading BCa cells to promote BCa lung colonization and tumor growth." (PMID 35626710, 2022). "Cxcr3 and Ccr5, the receptors for CXCL10 and CCL5, were broadly expressed on tumor-infiltrating lymphocytes, including regulatory T cells (Treg), gamma-delta (γδ) T cells, and NK cells." (PMID 36266311, 2022). "A small molecular weight antagonist of CXCR3, AMG487, was observed to block tumor development by inhibiting metastasis." (PMID 36612163, 2022). "In concordance with the L-R analysis, the image-based assays indicated the interacting cells mediated by CXCL10/CXCR3 and MIF/CD74 more closely co-localized with each other in tumor tissues as compared to those in NTL tissues." (PMID 35933472, 2022). "CXCL10 is a ligand for CXCR3 that is expressed on tumour-infiltrating lymphocytes and mediates CD8 T cell infiltration within tumour." (PMID 35148789, 2022). "In the literature, it is described that the CXCR3/CXCL9/CXCL10 signaling axis modulates the proliferation, migration and survival of tumor and endothelial cells." (PMID 35897689, 2022). "CXCL9, CXCL10, CXCL11, and CXCR3 recruited and activated immune cells, such as CD8 + T-cells, to suppress tumor progression through CXCL9,-10−11/CXCR3 axis, and they were down-regulated in the high-GATA3 group." (PMID 35647011, 2022). "A build-up of CXCR3 + CD4 + T cells in the tumour microenvironment as well as in the mesenteric and tumour-draining lymph nodes is seen when a favourable GM is present at baseline prior to ICI." (PMID 35876944, 2022). "Trafficking of CAR T cells to the tumor site depends on the appropriate matched expression of adhesion molecules and chemokine receptors (such as CXCR3 and CCR5) that allow for endothelial adhesion and transport, along with tumor-specific targeting." (PMID 35265074, 2022). "The authors showed that increased IL17A in serum from colorectal cancer patients activated STAT3, leading to the downregulation of CXCR3 in CD8+ T cells and reduced tumor infiltration." (PMID 35270020, 2022).
tumor (continued). "Regarding mouse malignant gliomas, when GL261 cancer cells were transfected with CXCL10 and subcutaneously transplanted into mice, tumor progression was significantly delayed, suggesting that the CXCL10/CXCR3 pathway can effectively inhibit tumor progression." (PMID 36479091, 2022). "To summarize, these data show consistent effects of CAFs on the downregulation of CXCR3 and the upregulation of CXCR4 expression on T cells in both 2D and 3D cultures, as well as when tumor spheroids were present in the 3D cultures." (PMID 35954489, 2022). "These NK cells at tumor sites lowly express CD57 and IFN-γ, while tumor-infiltrated NK cells exhibit higher expression of CXCR3." (PMID 35646915, 2022). "CXCL9, CXCL10, and CXCL11 bind to CXCR3 and regulate lymphocyte chemotaxis to mediate recruitment of tumor-infiltrating lymphocytes (TIL) for tumor-suppressor activity." (PMID 35269786, 2022). "In addition, accumulating evidence has suggested that the CXCL10 and CXCL11/CXCR3 axis could impose antitumor effects by recruiting Th1 cells, cytotoxic T cells, natural killer cells, and natural killer T cells to tumor sites and it has protumor effects on cancer cells expressing CXCR3." (PMID 36003333, 2022). "CXCL9 and CXCL11 recruit CXCR3+ T cells to the skin and overexpressed in rashes, higher CXCL9 and CXCL11 expression in macrophages had more CD8+ T cells in the tumor microenvironment." (PMID 36479091, 2022). "Targeting CXCL10/CXCR3 signaling inhibited the mobilization of Treg and EPC, attenuated early-phase liver graft injury, and prevented late-phase tumor recurrence/metastasis after transplantation." (PMID 35634295, 2022). "On the other hand, oral supplementation of non-responder patients with A. muciniphila upon FMT restored the anti-PDCD1 efficacy via IL12 by increasing the recruitment and infiltration of CXCR3+, CCR9+, CD4+ T cells into the mouse tumor site." (PMID 35463305, 2022). "Our observation contributes to the current consensus that the upregulation of CXCR3 and its ligands correlates with Th1 responses and RCC human/murine tumor regression." (PMID 36132332, 2022). "CXCL9/10/11 are ligands for CXC-chemokine receptor 3 (CXCR3), which is highly expressed on cytotoxic CD8+ T cells and IFN-γ-producing CD4+ T helper 1 cells, both of which provoke tumor cell killing and enhance inflammation in the TME." (PMID 36531014, 2022). "The present experiments were performed with the human tumor cell lines, A549, DLD-1, and MDA-MB- 231, which we previously characterized for expression as well as their use of CXCR4, CXCR3, and CXCR7 in CXCL12- and CXCL11-dependent chemotaxis." (PMID 36539774, 2022). "CXCR3 is a CXC chemokine receptor dominated by IFN-γ, which interacts with CXCL9, CXCL10, and CXCL11 to regulate tumor progression and cytokine secretion." (PMID 35571062, 2022). "CXCR3 is known to be expressed by both Th1 CD4+ T-cells and CD8+ effector T-cells and plays an important role in T-cell homing to the tumor site." (PMID 36230815, 2022). "CXCR3, which is expressed on Th1, macrophage and NK cells, and its ligands (CXCL9, CXCL10) is an important chemokine axis in tumor suppression via interferon-induced cell-mediated immunity and inhibition of angiogenesis." (PMID 36132332, 2022). "Among them, Cxcl9, Cxcl10, and Cxcl11 are most related to the recruitment of CD8+ T cells, as CXCR3, the cognate receptor for CXCL9 and CXCL10, is highly expressed in tumor infiltrated CD8+ T cells." (PMID 35145233, 2022). "As indicative of an enriched immune tumor microenvironment, we found CXCR3, ZAP70 and PTPN22; whereas others, such as TIMP1 and MAP2K3, had higher correlation with endothelial markers indicative of a tumor-induced angiogenic process." (PMID 35875157, 2022). "T-cell migration into the tumour microenvironment depends on the local production of specific chemokines, especially CXCL9 and CXCL10, which engage CXCR3 on the surface of CD8+ effector T cells." (PMID 36376335, 2022).
tumor (continued). "CXCL12 and CXCL11 affect tumor cell functions by either binding their prime receptors, CXCR4 and CXCR3, respectively, and/or CXCR7 as a common second chemokine receptor." (PMID 36539774, 2022). "Tumour-derived chemokines such as CXCL9, CXCL10, and CXCL11 are attracted by CXCR3 (expressed on activated CD8+ T cells), leading to their recruitment and development of anti-tumour immune response." (PMID 35406451, 2022). "TGF-β also suppresses chemokine receptor CXCR3 in CD8+ T cells, thereby limiting their trafficking to the tumor." (PMID 36106641, 2022). "The pro-inflammatory cytokine IFN-γ induces CXCR3 chemokines, e.g., CXCL-9 and CXCL-10, as part of the interferon-stimulated gene cluster that then attracts T cells into the tumor." (PMID 36611932, 2022). "The CXCR3 and CX3CR1 are mainly responsible for the tumor-suppressive lymphocytic infiltration into the tumor micromilieu." (PMID 35517862, 2022). "In mice, IFN-γ promoted CXCR3 expression on NK cells and also enhanced the production of its ligands, CXCL9 and CXCL10, on virus-infected cells and tumor cells;183,255 these ligands are important for NK cells’ anti-infection and anti-tumor properties." (PMID 35768424, 2022). "further revealed that silencing STAT3 in T cells allows CXCR3 (the receptor for CXCL10) to be expressed in CD8+ T cells, leading to CD8+ T cells effectively accumulating at tumor sites." (PMID 35530361, 2022). "In EGFR-mutant tumor cells cocultured with activated PBMCs, EGFR-TKI treatment increased CXCL10 in the supernatant; this activated CXCR3 in the tumor cells to induce the phosphorylation of Src and the NF-κB subunit, p65, and the expression of HIF-1α." (PMID 36612121, 2022). "CXCL9/10/11 exerted their biological effects related to EMT via CXCR3, which was upregulated in the invasive front of the CRC tumor tissues." (PMID 34233297, 2021). "CXCL9 is a critical chemokine that binds CXCR3 on T cells, enhancing recruitment of cytotoxic CD8+ T cells into the tumor and promoting the differentiation of inflammatory T helper type 1 (Th1) and Th17 CD4 T cells." (PMID 33508232, 2021). "In contrast, DPP4 inhibition enhanced tumor rejection by preserving the full-length biologically active form of CXCL10, leading to increased trafficking of CXCR3+ cells into the TME." (PMID 33757558, 2021). "During anti-tumor responses, CD8 effector T cells readily infiltrate B16F10 tumors in a CXCR3-dependent manner in response to CXCL9 and/or CXCL10 expressed by both tumor cells and CD11c+ cells." (PMID 34362825, 2021). "A three-step FACS gating strategy was used for the sorting of CD8+CXCR3+IFN-γ+ and CD8+CCR5+IFN-γ+ cells from tumor tissue suspension." (PMID 33469123, 2021). "DPP4 inhibition blocks the cleavage of CXCL10 by DPP4, thereby increasing the chemotaxis of immune cells towards tumour tissue via the cognate receptor of CXCL10, CXCR3." (PMID 34771657, 2021). "CXCR3 and CCR2 signaling leads to the recruitment of tumor-promoting immune cells, e.g., of TAMs, T cells and myeloid-derived suppressor cells (MDSC)." (PMID 34203660, 2021). "The expression levels of CXCR3 and CTLA4 were higher in tumor tissues than those in normal tissues (P < 0.05)." (PMID 34218795, 2021). "The chemokine receptors CXCR3 and CCR5 guide T cells to sites of infection, inflammation and tumors in response to chemokines released by inflammatory tissue and tumor cells." (PMID 33865435, 2021). "This in turn induces tumor cells and T cells to secrete CXCL10, mediating the recruitment of CXCR3+ T cells from the periphery." (PMID 33406104, 2021). "Heightened dual expression of the ligands for CCR5 and CXCR3 (CCL5 and CXCL9, respectively) positively correlates with the amount of tumor CD8a transcripts and patient survival in cancers of the ovary, breast, lung, colon, as well as melanoma." (PMID 34354714, 2021). "However, CXCR3 deficiency could not obviously reduce the tumor burden with no significant change of CD31 positive cells in tumor tissue." (PMID 33990548, 2021).